CD1B (CD1b molecule)
Description:
Antigen-presenting protein that binds self and non-self lipid and glycolipid antigens and presents them to T-cell receptors on natural killer T-cells.
Synonyms: CD1; R1
Tractability: Small molecule: a structure with a bound ligand is known; it has a high-quality binding pocket. Antibody: UniProt places it where antibodies can reach, with high confidence; its Gene Ontology location is reachable by antibodies, with high confidence; UniProt predicts a signal peptide or a membrane-spanning region. PROTAC: ubiquitination databases record sites on it.
Gene: Protein-coding gene on chromosome 1 (158,327,951 to 158,331,531, reverse strand). Ensembl gene ENSG00000158485.
Subcellular location: Cell membrane; Endosome membrane; Lysosome membrane
Subcellular location (Human Protein Atlas): Golgi apparatus; Vesicles; Cytosol
Pathways (Reactome):
Immune System: Immunoregulatory interactions between a Lymphoid and a non-Lymphoid cell
Gene Ontology:
Molecular function: protein binding; endogenous lipid antigen binding; exogenous lipid antigen binding; lipopeptide binding
Biological process: antigen processing and presentation, endogenous lipid antigen via MHC class Ib; antigen processing and presentation, exogenous lipid antigen via MHC class Ib; immune response; positive regulation of T cell mediated cytotoxicity
Cellular component: cell surface; endosome membrane; lysosomal membrane; plasma membrane; external side of plasma membrane; membrane
Genetic constraint (gnomAD): Loss-of-function variants: 43 observed, 41.58 expected, observed/expected ratio (o/e) 1.03, 90% interval 0.81 to 1.33. The upper end of that interval is the gene's LOEUF score, 1.33, which puts it in group 5 of 6, group 1 being the genes least tolerant of losing a copy. Missense variants: 488 observed, 416.61 expected, observed/expected ratio (o/e) 1.17, 90% interval 1.09 to 1.26. Synonymous variants: 188 observed, 156.54 expected, observed/expected ratio (o/e) 1.2, 90% interval 1.07 to 1.36.
Homologues: Orthologues: chimpanzee CD1B (99% identical), macaque CD1B (89% identical), pig CD1B (70% identical), guinea pig Cd1b3 (68% identical), rabbit CD1B (68% identical), guinea pig Cd1b2 (67% identical), guinea pig Cd1b1 (67% identical), guinea pig Cd1b4 (63% identical), zebrafish mhc1laa (20% identical), zebrafish mhc1lfa (20% identical), zebrafish mhc1lba (19% identical), zebrafish mhc1lda (19% identical), and 5 more. Paralogues in human: CD1C (60% identical), CD1A (58% identical), CD1E (55% identical), CD1D (53% identical), HLA-A (25% identical), HLA-B (25% identical), HLA-E (25% identical), HLA-F (25% identical), HLA-G (24% identical), HLA-C (24% identical), MR1 (20% identical), FCGRT (20% identical), and 10 more.
Diseases named in the same sentence as CD1B in open-access papers:
CD1B is named in the same sentence as 52 diseases in open-access papers, as found by Europe PMC text mining. Sharing a sentence is not in itself a finding about the gene and the disease. The quoted sentences say what the papers report.
tuberculosis (20 papers, 2010 to 2025). A chronic, recurrent infection caused by the bacterium Mycobacterium tuberculosis. "This is the case of the Mtb-specific sulfoglycolipid Ac2SGL, which is presented by CD1b molecules and is recognized by T cells found in tuberculosis (TB) patients and in individuals with latent infections." (PMID 33162982, 2020). "MA broadly distributed within endosomal compartments of dendritic cells and MA-specific CD1b-restricted T cells can be detected in the blood and disease sites of tuberculosis patients and demonstrated a memory response upon ex vivo re-stimulation." (PMID 30538700, 2018). "Through mutagenesis and study of T cells from tuberculosis patients, we identify a consensus CD1b footprint of TCRs present among GEM T cells." (PMID 27807341, 2016). "The development of CD1b tetramers has recently allowed to track mycobacteria-specific CD1b-restricted T cells in the blood of individuals with active tuberculosis or previous M. tuberculosis (MTB) exposure." (PMID 26284072, 2015). "CD1b-restricted T cells specific to Mtb lipids including mycolic acid (MA), an immunodominant lipid antigen and the component of the mycobacterial cell wall, have been identified in patients with tuberculosis (TB)." (PMID 37877801, 2023). "Additionally, mRNA and protein expression levels of ALDH1A2 and DC marker CD1B were lower in tuberculosis lung tissues than in normal lung." (PMID 31167948, 2019). "The reduced frequency of mycobacteria-specific CD1b-restricted T cells may contribute to the increased incidence of tuberculosis in this group." (PMID 29616036, 2018). "In addition, immunizations with glucose monomycolate, a glycolipid that was already known to be presented by human CD1b during leprosy and tuberculosis, showed that this compound is also immunogenic in cattle." (PMID 25815476, 2015). "The study of the recognition of the recombinant phage in ELISA and immunohistochemistry showed the recognition of CD1b:Ac2SGL complexes and cells in human lung tissue from a tuberculosis patient respectively, suggesting the specific recognition of the lipid-CD1b complex." (PMID 23458512, 2013). "Cell wall mycolic acids (MA) from Mycobacterium tuberculosis (M.tb) are CD1b presented antigens that can be used to detect antibodies as surrogate markers of active TB, even in HIV coinfected patients." (PMID 20875402, 2010). "Biased usage of TRBV4-1 has been reported for CD1b-restricted T cells from blood and TB pleural effusions, suggesting that such TCRs are clinically relevant to host response in TB disease and could be biomarkers of M. tuberculosis infection." (PMID 39718834, 2024). "We developed CD1b tetramers loaded with synthetic DAT to study recognition of DAT by T cells ex vivo in both healthy individuals and tuberculosis patients." (PMID 33479373, 2021). "GroMM-specific, CD1b-restricted T cells have been detected in the circulation of patients with latent, but not active tuberculosis." (PMID 38203570, 2023). "Finally, we examined the ex vivo transcriptional profiles of SGL-specific T cells in patients with active tuberculosis and found canonical transcription factor lineages among CD4 and CD8 CD1b-restricted T cells." (PMID 35013257, 2022). "Moreover, CD1b mutagenesis studies showed that the ‘energetic hot spot' matched with the invariant TCR α-chain footprint of two characterized GEM TCRs, as well as polyclonal GEM T cells isolated from tuberculosis patients." (PMID 27807341, 2016). "However, the mechanism leading to the decrease in CD1B and ALDH1A2 in human TB lung is unclear given M. tuberculosis infection has been described to result in DC cell death, transmigration away from the lung, and defective DC differentiation." (PMID 31167948, 2019).
tuberculosis (continued). "Thus, the clarification of how MPM is synthesized by mycobacteria and how it is recognized by the host immune system sheds light on distinct aspects of human tuberculosis that have never been appreciated in previous studies of CD1a−, CD1b− and MHC-restricted T-cell responses." (PMID 22536277, 2012).
prostate carcinoma (6 papers, 2019 to 2022). A carcinoma that arises from epithelial cells of the prostate gland. "A previous study has reported that the expression patterns of CD1 molecules in cancer cells differ from those in normal cells, and dysregulation of CD1B was associated with the prognosis of patients with prostate cancer." (PMID 35401707, 2022). "In this study, using two-stage genetic association studies, we identified CD1B rs3181082 as an independent prognostic factor related to disease recurrence in patients with prostate cancer." (PMID 31783478, 2019). "Similar to our study, in prostate cancer, the decreased levels of CD1B expression could be linked to the poorer disease-free survival." (PMID 34364366, 2021). "More recently, low expression of CD1B was reported to be correlated with poorer biochemical recurrence-free survival in prostate cancer." (PMID 32867782, 2020). "To further confirm the biological functions of CD1B during prostate cancer progression, we investigated the correlation of CD1B expression with disease outcomes in publicly available microarray datasets." (PMID 31783478, 2019). "Low CD1B expression correlated with poorer biochemical recurrence-free survival in prostate cancer." (PMID 36727052, 2022). "Our results indicate that CD1B rs3181082 correlates with prostate cancer outcomes and may provide information for the improved prediction of prostate cancer progression and guide disease monitoring." (PMID 31783478, 2019). "Further studies of CD1B rs3181082 may identify new biological pathways affecting postoperative progression in prostate cancer." (PMID 31783478, 2019). "Besides prostate cancer, CD1B is also expressed in thyroid, liver, colorectal, breast, urothelial, and stomach cancers according to the Human Protein Atlas database." (PMID 31783478, 2019). "Further functional analyses supported the involvement of CD1B in prostate cancer progression." (PMID 31783478, 2019). "Our results indicated that CD1B rs3181082 confers prostate cancer progression and may help improve clinical prognostic stratification." (PMID 31783478, 2019). "CD1B confers prostate cancer progression and may help improve clinical prognostic stratification." (PMID 36727052, 2022). "Since CD1B is abundantly expressed on the myeloid cells, it is possible that rs3181082 or other untyped functional SNPs in linkage disequilibrium have a modest effect on the function of CD1B, which in turn has an impact on tumour immunity and clinical outcomes in patients with prostate cancer." (PMID 31783478, 2019).
leprosy (5 papers, 2015 to 2023). Leprosy is a chronic infectious disease affecting primarily the skin and peripheral nervous system. "In leprosy, a human mycobacterial infection, IL-32 has been shown to promote the differentiation of monocytes into CD1b+ DCs upon NOD2 activation." (PMID 37727785, 2023). "Accordingly, the expression of NOD2 and IL-32, as well as the number of CD1b+ DCs were higher in tuberculoid than in lepromatous leprosy lesions, indicating a relevant mechanism to control the dissemination of infection." (PMID 37727785, 2023). "CD1b+ DC are potent antigen-presenting cells in induction of an adaptive T cell response in leprosy." (PMID 27297389, 2016). "Conversely, PEIPC has been reported to elicit IL-8 and MCP-1 secretion from endothelial cells by activating the EP2 receptor, but also appears to negatively regulate CD1b expression and DC maturation in human leprosy." (PMID 25770125, 2015). "IL-32 induction was measured, since it is specific to NOD2 versus TLR2/1 activation and is required to induce CD1b+ DC differentiation and cross-presentation, and its expression at the site of disease correlates with the self-limited versus progressive form of leprosy." (PMID 27297389, 2016). "CD1B+ DCs were found in the granulomas derived from patients with the self-limiting form of leprosy (tuberculoid); in contrast, DCs were absent in the lesions derived from patients with the disseminated form of leprosy (lepromatous)." (PMID 31167948, 2019).
colon cancer (4 papers, 2020 to 2023). "Furthermore, the effects of the IRGs on colon cancer development remain unclear, although cancer progression has been linked to CD1B, XCL1, PLCG1, NGF, and OXTR." (PMID 32508884, 2020). "An increasing body of bioinformatics analyses has identified CD1B as prognostic biomarker in colon cancer and lung cancer." (PMID 36814908, 2023). "High expression of CD1B and CCL22 was associated with longer OS for colon cancer patients." (PMID 34497681, 2021).
Granuloma (4 papers, 2020 to 2024). A compact, organized collection of mature mononuclear phagocytes, which may be but is not necessarily accompanied by accessory features such as necrosis. "Guinea pigs develop necrotic core granulomas, and their macrophages exhibit surface CD1b and CD1c, making them a beneficial small animal model for replicating human TB." (PMID 39949719, 2024). "Interestingly, the frequency of CD1b + cells in TB granuloma lesions reflects a large proportion of the initial cells recruited in the early response to Mtb infection, as evidenced by the increased proportion of CD1b+ cells among all granuloma-associated infiltrate at day 14 of infection." (PMID 39494875, 2024). "Previous studies have also shown increased expression of CD1b proteins in dermal granulomas of individuals with tuberculoid leprosy and human pulmonary TB granulomas raising the potential for recruitment of CD1b-restricted T cells to sites of infection." (PMID 34914694, 2021). "In the liver, CD1b+ cells were observed in the inflammatory infiltrates surrounding portal spaces and in the periphery of granulomas." (PMID 32131896, 2020).
lung adenocarcinoma (4 papers, 2020 to 2024). A carcinoma that arises from the lung and is characterized by the presence of malignant glandular epithelial cells. "We found one article by searching for CD1b as a potential prognostic biomarker associated with tumor mutation burden and promotes antitumor immunity in lung adenocarcinoma." (PMID 38099311, 2023). "Similarly, in lung adenocarcinoma patients, CD1B has been identified as an independent prognostic factor." (PMID 39000502, 2024).
psoriasis (4 papers, 2017 to 2023). An autoimmune condition characterized by red, well-delineated plaques with silvery scales that are usually on the extensor surfaces and scalp. "However, recent studies from our lab demonstrated a pathogenic role of CD1b-autoreactive T cells in hyperlipidemia-associated psoriasis-like skin inflammation." (PMID 30061888, 2018). "For example, CD1d was upregulated in the psoriatic plaques from patients with active psoriasis, while patients with active psoriasis and dyslipidemia exhibited increased CD1b expression in skin." (PMID 30061888, 2018). "Recent work by our lab showed that upon induction of hyperlipidemia, CD1b-autoreactive T cells contributed to the development of psoriasis-like skin inflammation, characterized by a Th17 phenotype." (PMID 30061888, 2018). "Our lab showed that serum from hyperlipidemic mice enhances IL-6 production by DCs, driving IL-17A production by autoreactive CD1b-restricted T cells in a model of psoriasis." (PMID 30061888, 2018). "We have recently shown that under conditions of hyperlipidemia, presentation of phospholipids and cholesterol by CD1b to cognate T cells drove the development of an inflammatory skin disease resembling psoriasis." (PMID 30061888, 2018). "CD1-restricted T cell autoreactivity can manifest in a range of disease settings, including CD1b-mediated psoriasiform inflammation, CD1a-mediated contact hypersensitivities, allergic responses to bee venom and house dust mites, and psoriasis." (PMID 29054999, 2017).
Autoimmunity (3 papers, 2017 to 2021). The occurrence of an immune reaction against the organism's own cells or tissues. "On the other hand, such cells have the potential to cause autoimmunity, as was recently demonstrated in mice that expressed human CD1b and phospholipid specific TCR." (PMID 30610190, 2019). "If such CD1b-specific T-cells are generally present in human donors, the question arises as to whether they would cause autoreactivity or autoimmunity upon contact with any CD1b-expressing cell." (PMID 30610190, 2019). "Because CD1b and cellular phospholipids are expressed by macrophages and myeloid DCs in vivo, basic questions arise regarding control of potentially deleterious T cell reactivity that could cause autoimmunity." (PMID 29054999, 2017).
autoimmune disease (2 papers, 2011 to 2019). A disorder resulting from loss of function or tissue destruction of an organ or multiple organs, arising from humoral or cellular immune responses of the individual to their own tissue constituents. "Also, clear evidence for immune response to phospholipids via CD1b and CD1d invites consideration of possible B cell–T-cell interactions in the anti-phospholipid antibody syndrome, an autoimmune state associated with systemic lupus erythematosus and other autoimmune diseases." (PMID 30610190, 2019). "This study raises the possibility that CD1b and phospholipids might play an unrecognized role in autoimmune disease." (PMID 30610190, 2019).
colon adenocarcinoma (2 papers, 2021). "The levels of CD1B expression correlated with the infiltration levels of neutrophils (r= 0.468, p= 3.31E-23) and dendritic cells (r = 0.505, P = 2.05E-27) in colon adenocarcinoma (COAD) samples." (PMID 33536348, 2021). "The outcomes reveal the positive correlation of the CD1B expression level with the infiltrating levels of neutrophils (r = 0.468, p = 3.31E-23) and Dendritic Cells (r = 0.505, P = 2.05E-27) in colon adenocarcinoma (COAD)." (PMID 34364366, 2021).
latent infection (2 papers, 2020). "The initial goal of this study was to measure the frequency of CD1b and mycobacterial lipid-reactive T cells using CD1b tetramers in a cohort of 150 human subjects that had either Mtb exposure but no documented infection, latent infection, or active TB." (PMID 32117314, 2020).
lymph node metastasis (2 papers, 2020 to 2022). "The expression of CD1B was significantly lower in cases involving advanced-stage disease, lymph node metastasis, and distant metastasis." (PMID 32508884, 2020). "This study constructed a prognostic model of genes related to lymph node metastasis in COAD and found that PMCH, CD1B, NAT1, NKAIN4, and LRP2 have prognostic, predictive values." (PMID 36727052, 2022).
lymphoma (2 papers, 2019 to 2022). A malignant (clonal) proliferation of B- lymphocytes or T- lymphocytes which involves the lymph nodes, bone marrow and/or extranodal sites. "Indeed, it has been shown that CD1B-restricted self-lipid reactive T cells respond more potently to tumour-derived phospholipids than lipids extracted from normal cells, and the adoptive transfer of these T cells into mice harbouring CD1B-expressing lymphoma results in tumour control." (PMID 31783478, 2019). "IL-10 was detected at the nonlymphoma ATA B cell stage, and the lymphoma stage showed strongly increased IL-10 expression and CD1b/Mac1+IL-6+IL-10++ in ATA B lymphoma." (PMID 36050343, 2022).
multiple sclerosis (2 papers, 2011 to 2015). A progressive autoimmune disorder affecting the central nervous system resulting in demyelination. "Of note, sulfatide can also be presented by CD1b, CD1c, and CD1d, which suggested a possible contribution of CD1-restricted T cells to the autoimmune response in multiple sclerosis (MS)." (PMID 26284072, 2015).
Pleural effusion (2 papers, 2015 to 2024). The presence of an excessive amount of fluid in the pleural cavity. "For example, CD16+ monocytes in pleural effusion represent effective APCs since these monocytes express receptors for Mtb recognition and antigen presentation (DC-SIGN, MR, CD11b, and CD1b)." (PMID 26339660, 2015).
acute GVHD (1 paper, 2018). "Additionally, a prospective investigation of epidermal XBP-1s+, CD1b+ DCs and their potential involvement in the pathogenesis of acute GVHD warrants future study." (PMID 30574153, 2018). "Preliminary data from a pilot cohort of patients undergoing allogeneic HCT (5 with acute GVHD and 5 without), suggests that the amount of intracellular XBP-1s is significantly increased in CD1b+, epidermal DCs among skin biopsies from patients with acute GVHD compared to no GVHD controls." (PMID 30574153, 2018).
atopic dermatitis (1 paper, 2014). "In the acute phase of atopic dermatitis, these cells coexpress CD1b/c and produce chemokines that attract TH2 cells." (PMID 24877070, 2014).